PDPN (podoplanin)
Diseases named in the same sentence as PDPN in open-access papers (continued):
Sharing a sentence is not in itself a finding about the gene and the disease.
cancer (continued). "PDPN expression has been reported in ectopic lymphoid tissues in instances of chronic inflammation and cancer, but only on FRC-like stromal cells." (PMID 22988448, 2012). "Podoplanin is a possible target for development of novel therapies, and its expression has to be studied in other settings to completely understand its role in cancer development and progression." (PMID 21773035, 2011). "Here, we investigated the role of cancer cell-associated podoplanin in the progression of lung SCC using an animal model, and found novel functions of podoplanin as a suppressor for cancer progression." (PMID 21034514, 2010). "Transfection studies with cultured normal and cancer cells were employed to investigate the function of podoplanin in vitro." (PMID 17179989, 2007). "In both cases, inhibition of RhoA modulation led to reduced cell motility, strengthening the notion that the regulation of RhoA activity is causally involved in the pro-migratory phenotype observed in podoplanin-expressing cancer cells." (PMID 17179989, 2007). "The expression of podoplanin in human cancers raises the possibility to employ podoplanin expression as an immunohistochemical marker for diagnosis and prognosis." (PMID 17179989, 2007). "These in vitro data support the concept that podoplanin expression in human cancers promotes migration and invasion of cancer cells in the absence of a cadherin switch and EMT." (PMID 17179989, 2007). "Similarly, soluble podoplanin (sPDPN) has been identified as a biomarker in malignancies and inflammatory diseases such as cancer and COVID-19, highlighting its potential and prognostic significance." (PMID 41421102, 2025). "To test this hypothesis, we performed SEM observations of PDPN-positive sites in these thoracic malignant tumors using the NanoSuit-CLEM method to develop a simple and practical approach for routine pathological diagnosis." (PMID 40428290, 2025). "Additionally, PDPN modulates the activities of Rho-family GTPases, particularly RhoA, which contributes to the pro-migratory phenotype of PDPN-expressing cancer cells." (PMID 40666093, 2025). "In this workflow, PDPN immunohistochemistry alone, rather than a multi-antibody panel, served as the initial diagnostic step for epithelioid-type thoracic malignant tumors located in the pleural region." (PMID 40428290, 2025). "The oncogenic glycoprotein podoplanin (PDPN) is commonly overexpressed in various cancer types, where it facilitates metastatic dissemination through interactions with CLEC-2 on platelets and other stromal cells, thereby contributing to stromal immunosuppression." (PMID 41573582, 2025). "The epitope of LpMab-2 includes O-glycosylation of PDPN expressed in cancer cells." (PMID 40688491, 2025). "This is a promising result, and targeting PDPN or CLEC-2 could lead to novel possibilities for cancer treatment and prevention." (PMID 40693815, 2025). "The membrane protein podoplanin (PDPN) is a well‐known cancer‐promoting molecule." (PMID 39764562, 2025). "The latest drug research focuses on anti-PDPN antibodies for the treatment of various cancer types." (PMID 38504248, 2024). "Furthermore, the study reported that up to 88% of VTE cases showed immunohistochemically positive cancer cells for tissue factors (TF) or PDPN." (PMID 39682237, 2024). "Therefore, there is significant interest in understanding how changes in cancer cells’ behavior affect this protein, and blocking PDPN shows promise as a potential therapeutic approach for GBM cancer treatment." (PMID 39682237, 2024). "MMP2 and PDPN were highly expressed in less than half of cancers." (PMID 39335130, 2024). "In addition to its involvement in cancer progression, recent studies indicate that the PDPN/CLEC-2 signaling axis is crucial in various physiological and pathological conditions such as blood cell generation, inflammatory response, and thrombus formation." (PMID 39451677, 2024).
cancer (continued). "PDPN is involved in malignant tumor progression by promoting invasiveness and metastasis." (PMID 39594582, 2024). "Hence, the PDPN/CLEC-2 axis is a potential therapeutic target for anti-cancer metastasis and anti-cancer-associated thrombosis." (PMID 39451677, 2024). "NZ-1, an anti-PDPN mAb (rat IgG2a), showed a higher reactivity to those cancer cell lines." (PMID 39594582, 2024). "In observational studies of various types of cancer, platelet aggregation is PDPN dependent." (PMID 40741180, 2024). "PDPN-expressing cancer cells are highly pernicious, with a mutant aptitude to form stem cells." (PMID 39682237, 2024). "Interestingly, LpMab monoclonal antibody series have been reported to specifically recognize aberrantly glycosylated PDPN in cancer cells, thereby avoiding adverse reactions." (PMID 38504248, 2024). "The CLEC-2-podoplanin interaction is a target for cancer treatment." (PMID 38504248, 2024). "The interaction between ERM proteins and PDPN is essential for PDPN-mediated rearrangement of the actin cytoskeleton, modulates small Rho GTPases, and facilitates epithelial-mesenchymal transition during embryogenesis and cancer progression." (PMID 40741180, 2024). "Furthermore, cancer cells promote platelet activation and aggregation through the expression of Podoplanin (PDPN) and the secretion of platelet agonists such as ADP and thrombin Plasminogen activation inhibitor-1 (PAI-1)." (PMID 38611118, 2024). "On the one hand, studies revealing an impact of IDH1 mutation on VTE suggested that this genetic event may drive methylation-mediated down regulation of two procoagulant effectors, TF and PDPN in cancer cells." (PMID 38188342, 2023). "First, we analyzed the expression profile of PDPN in pan-cancer." (PMID 36434176, 2023). "Podoplanin (PDPN) has been proved to be involved in the progression of various cancers." (PMID 36156321, 2023). "PDPN expression was correlated with the 14 functional states in 10 cancer types." (PMID 37434432, 2023). "Podoplanin expressed in cancer cells activates platelets through CLEC-2." (PMID 37693009, 2023). "In addition, cell identities of clusters were correctly identified even when the key canonical marker genes (e.g., PDPN and FAP of cancer-associated fibroblast) were out of the input gene list." (PMID 37924118, 2023). "PDPN overexpression has also been noted in inflammatory diseases, tissue damage and a wide range of cancers, and is directly correlated with disease outcomes, but the downstream signalling pathways and mechanisms of action of PDPN are still not fully understood." (PMID 37161290, 2023). "The CLEC-2/PDPN axis was discussed as a promising drug target for cancer treatment." (PMID 38067218, 2023). "Furthermore, we exprlored the expression of marker genes (PDPN, THY1, PDGFRB, PDGFRA,and POSTN) for cancer-associated fibroblasts (CAFs) in different cell types, and found that all marker genes were highly expressed in fibroblasts." (PMID 36973787, 2023). "However, recent studies have reported that PDPN is also expressed in cancer cells, dendritic cells, and inflammatory macrophages, especially CAFs." (PMID 37143134, 2023). "Changes in PDPN had been reported in different human cancers." (PMID 36156321, 2023). "It has been revealed that PDPN expression level is upregulated by TGF‐β in other cancer types." (PMID 37434432, 2023). "podoplanin was promoting aggressive phenotypes in PTC through the epithelial-mesenchymal transition (EMT) signaling pathway, which is associated with increased invasiveness and metastasis in cancer cells." (PMID 38089632, 2023). "Pre-clinical studies have shown that blocking podoplanin decreased thrombosis onset in cancer models, thus demonstrating that targeting podoplanin in cancer patients may be a feasible strategy in reducing thrombosis." (PMID 36361963, 2022).
cancer (continued). "Furthermore, the gene expression profiles of immunosuppressive cytokines were compared using The Cancer Genome Atlas microarray lung SCC data between a PDPN-high group and a PDPN-low group." (PMID 35159384, 2022). "Another approach for cancer-specific anti-PDPN mAbs has been developed." (PMID 35159384, 2022). "Podoplanin is a molecule that is also expressed by certain types of cancer cells." (PMID 36361963, 2022). "Furthermore, the proportion of lymphatic endothelial cells (End-C4: PDPN + ) was constantly decreased from AIS to IAC, while the fraction of cancer-associated fibroblasts (C1) was significantly decreased in IAC compared with AIS and MIA." (PMID 36434043, 2022). "Podoplanin and Ki-67 are two important markers of cancer progression." (PMID 36077194, 2022). ",34, 35, 36 Lp2 recognizes cancer-type PDPN, which is extraordinarily glycosylated." (PMID 35991754, 2022). "In this review, we describe the mechanistic basis and diverse roles of PDPN in the malignant progression of tumors and discuss the possibility of the clinical application of PDPN-targeted cancer therapy, including cancer-specific monoclonal antibodies, and chimeric antigen receptor T technologies." (PMID 35159384, 2022). "Using The Cancer Genome Atlas Lung Squamous Cell Carcinoma database, several genes are highly expressed in cases with PDPN‐expressing CAFs, including interleukin (IL)‐1A, IL‐1B, IL‐6, IL‐10, CCL2, colony‐stimulating factor 1 (CSF1), FGF2, galectin 1, PDGFA, PDGFB and TGF‐β1." (PMID 35603909, 2022). "Furthermore, we found that the expression of podoplanin (PDPN), a known marker of lymphatic vessels as well as cancer-associated fibroblasts (CAF), was markedly upregulated in the metastatic lesions of DI-E-RAMP2-/- mice." (PMID 35625516, 2022). "Future studies to elucidate the roles of podoplanin during cancer invasion and metastasis could therefore help to establish new podoplanin-based anti-cancer therapies." (PMID 35163233, 2022). "However, podoplanin expression correlates with a good prognosis in cancers such as SCC of the uterus, cervix, and lung." (PMID 35163233, 2022). "Previous studies have indicated that PDPN played a role in regulation of a variety of cellular signalling pathways, including proliferation, contractility, migration, chronic inflammation and cancer, which was dependent on binding of PDPN to its ligands." (PMID 35652821, 2022). "The expression of PDPN is high in a number of different cancers, including HNSCC." (PMID 36077194, 2022). "In an immunohistochemical analysis for PDPN and E-cadherin in the collective invading front of human tumors, PDPN is detectable exclusively in the outer cell layer of the invading front, whereas E-cadherin is expressed in all carcinoma cells." (PMID 35159384, 2022). "A multitude of studies have shown that PDPN expression is increased in cancer and frequently correlates with poor prognosis, suggesting an important role for this protein in cancer progression and/or immunoevasion, and pointing towards PDPN as a potential target for cancer therapeutics." (PMID 34879110, 2021). "It has been reported that PDPN mediated TCIPA-induced EMT process in human cancer cell lines." (PMID 34987523, 2021). "Theoretically, neutralising monoclonal antibodies could be used to target antigens involved in cancer development, and a recent phase I/II clinical trial has taken this approach with chimeric mouse/dog anti-podoplanin antibody." (PMID 34822659, 2021). "Similarly, cancer cell lines with high endogenous PDPN expression levels, such as LN319 and Colon-26, showed induced platelet aggregation, which was attenuated by pre-incubation with an anti-CLEC2 antibody." (PMID 34987523, 2021). "In this regard, it is plausible that the PDPN-ERM axis could be recruited by tumors bound to platelets via CLEC2-PDPN interaction, conferring cancer cells metastatic potentials." (PMID 34987523, 2021).
cancer (continued). "Overexpression of PDPN in vascular endothelial cells could also induce thrombo-inflammation, possibly promoting PDPN-induced cellular interactions between platelets, cancer cells and endothelial cells." (PMID 34322381, 2021). "Cytoplasmic PDPN has been previously reported in certain cancer cell types and could reflect cellular malfunction regarding the segregation of the protein to the cell surface." (PMID 34065661, 2021). "The fibroblasts encompassed 4 major populations defined by key cancer-associated fibroblast (CAF) markers, including fibroblast activation protein (FAP), alpha smooth muscle actin (αSMA, ACTA2), podoplanin (PDPN), and platelet-derived growth factor receptor beta (PDGFRβ)." (PMID 34385456, 2021). "Thus, dysregulation of ERM proteins takes part in cancer promotion and progression, possibly in an interdependent manner with PDPN." (PMID 34987523, 2021). "Likewise, injection of PDPN mAb (MS-1) remarkably suppressed platelet aggregation as well as lung metastasis in the murine cancer metastasis model." (PMID 34987523, 2021). "Cancer cell-resident podoplanin (PDPN) was proposed as a key regulator of this process." (PMID 34322381, 2021). "Moreover, PDPN can induce migration ability in cancer cells that bypass the EMT process via filopodia formation." (PMID 34987523, 2021). "Podoplanin is another lymphatic specific maker, but it is also used as a cancer biomarker." (PMID 34847944, 2021). "Alternative mechanisms of platelet inhibition that may benefit cancer survival include inhibition of CLEC-2, a platelet receptor that causes platelet activation and binds to podoplanin on cancer cells." (PMID 34988471, 2021). "We next investigated whether the deletion of cancer cell expressed podoplanin also affected the lymphatic vasculature in the two-stage chemical carcinogenesis model." (PMID 32599908, 2020). "Podoplanin could be a useful prognostic marker and indicates better differentiation for LUSC patients, and the value of PDPN expression as a marker for cancer stem cells in LUSC should be critically evaluated in future studies." (PMID 32408907, 2020). "Moreover, aggregates of circulating cancer cells with platelets through the binding of PDPN to CLEC-2 have been reported to further promote the process of hematogenous metastasis." (PMID 32858947, 2020). "For example, designing CARs to target cancer-specific post-translational modifications such as Tn-glycosylated podoplanin (Tn-PDPN) would be expected to result in fewer off-cancer effects as the 237Ab-derived 237 CAR T cells target Tn-PDPN, which is not present on normal tissue." (PMID 32903482, 2020). "Interestingly, podoplanin-positive cancer cell also overexpresses endothelin-1 (ET-1), a promoter of lymphangiogenesis, which supposedly functions by combining ENDRB that expresses on endothelial cells." (PMID 33363035, 2020). "A loss or a decrease in EpCAM expression and an increase in mesenchymal markers such as N-cadherin, vimentin, and podoplanin in cancer cells may accompany the EMT." (PMID 32071283, 2020). "With the combination of NIR-PIT and CasMab technology for PDPN targeting, we could achieve ideal selective cancer cell death targeting PDPN." (PMID 32326079, 2020). "The interaction with ERM proteins is critical for podoplanin-mediated rearrangement of the actin cytoskeleton and modulation of small Rho GTPases, and is involved in promoting epithelial–mesenchymal transitions (EMTs) during embryonic development and cancer." (PMID 30736372, 2019). "Therefore, blocking the podoplanin-CLEC-2 interaction by a small-molecule compound is a potential therapeutic strategy to prevent cancer metastasis and invasion." (PMID 31553741, 2019). "Likewise, the levels of soluble podoplanin in plasma were found to increase in patients with a wide variety of cancers compared to normal individuals, as well as in patients with metastasis with respect to patients with non-metastatic tumors." (PMID 30736372, 2019).
cancer (continued). "While the research about the implication of podoplanin in patho-physiological processes, such as immune response, thrombosis, inflammation, and cancer, experienced notable advances in the last decade, there are still many issues for which we have incomplete knowledge." (PMID 30736372, 2019). "The high expression of the cancer-associated markers FAP and podoplanin in normal skin fibroblasts, could suggest an upregulation of some markers through serial passaging." (PMID 31068935, 2019). "Podoplanin is a platelet activator secreted by cancer cells." (PMID 30791448, 2019). "On the other hand, podoplanin presentation could have pathological consequences in the context of chronic inflammation, cancer and thrombosis." (PMID 30745334, 2019). "The expression of human PDPN (hPDPN) has been reported in several malignant tumors, including malignant brain tumors, malignant mesotheliomas, oral squamous cell carcinomas, esophageal cancers, lung cancers, osteosarcomas, chondrosarcomas, and testicular tumors." (PMID 30997422, 2019). "si-hVDAC1 thus acts as an antagonist to such PDPN pro-cancer activity." (PMID 31195298, 2019). "PDPN expression has been found in various human tumors and is considered to be a marker of cancer." (PMID 30654768, 2019). "Podoplanin signalling through ROCK (herein referring to both ROCK1 and ROCK2) has been reported to enhance the ability of cancer-associated fibroblasts (CAFs) to invade collagen matrices in vitro and fibroblast-like cell lines to migrate across Transwell filters." (PMID 30745334, 2019). "Furthermore, high ectopic expression of PDPN has been shown to result in enhanced cancer cell migration, lymphangiogenesis and metastasis in the human MCF7 breast carcinoma xenograft model." (PMID 30654768, 2019). "Interestingly, the levels of soluble podoplanin were reduced after treatment of patients with chemotherapy or surgery followed by chemotherapy, pointing to soluble podoplanin as a specific cancer biomarker." (PMID 30736372, 2019). "Since the migration and invasion of cancer cells are crucial factors responsible for cancer progression, we first examined whether PDPN may impact the ability of cells to migrate." (PMID 30654768, 2019). "The PDPN-expressing cells within the matrigel plugs were predominantly co-immunolabeled with the LEC marker LYVE1 but did not express the cancer-associated fibroblast marker αSMA." (PMID 30592710, 2018). "Importantly, a particular antibody that reacts with podoplanin-expressing cancer cells but not with the one from normal cells has been successfully generated and will be useful for molecular targeting therapy against podoplanin-expressing cancer cells only." (PMID 29497419, 2018). "The PDPN is a lymphatic vessel marker (clone D2-40; one of the anti-humanPDPN monoclonal antibodies: mAbs) and expression of PDPN by stromal CAFs has been reported to be a prognostic indicator in various types of cancer." (PMID 29765527, 2018). "Thus, by decreasing PDPN expression, si-hVDAC1 countered the pro-cancer activity of PDPN in terms of cancer progression and metastasis." (PMID 30544833, 2018). "Immunohistochemical staining was done to evaluate the expression of PDPN in cancer tissues." (PMID 28702871, 2018). "Recently, we successfully produced cancer-specific mAbs (CasMabs) against human podoplanin." (PMID 29854293, 2018). "We need to know more details about the mechanism for targeting podoplanin in cancer (see Sect." (PMID 28674748, 2017). "PDPN on cancer cell surfaces plays a role in cancer cell-induced platelet aggregation." (PMID 28059107, 2017). "Therefore in cancer cell biology it is very difficult to define the specific role of individual proteins expressed by CAFs, including podoplanin, on properties such as proliferation, survival, invasion and ability to metastasize." (PMID 28938000, 2017). "A positive control, chLpMab‐7, detected PDPN expression in two cancer cell lines." (PMID 28332312, 2017).